IGF2BP3 (insulin like growth factor 2 mRNA binding protein 3)
Diseases named in the same sentence as IGF2BP3 in open-access papers (continued):
Sharing a sentence is not in itself a finding about the gene and the disease.
cancer (continued). "Subsequently, the combination of circFNDC3B and insulin‐like growth factor 2 binding protein 3 (IGF2BP3), an RNA binding protein (RBP) connected with varieties of malignant tumors, was detected by RIP assay, and the binding of IGF2BP3 and CD44 mRNA was identified by RNA pull down assay." (PMID 36793611, 2023). "We found that IGF2BP3 was expressed differently in different immune subtypes (C1: wound healing, C2: IFN-gamma dominant, C3: inflammatory, C4: lymphocyte depleted, C5: immunologically quiet, C6: TGF-b dominant) of 29 cancer types." (PMID 36761737, 2023). "Interestingly, 14 of the 29 TCGA cancer types, including the three with the enriched senescence module, show ploidy-upregulation of IGFBPs and IGF2BPs, IGF2BP1 and IGF2BP3 being the most frequently encountered." (PMID 36499258, 2022). "Based on the lack of IGF2BP3 in most normal tissues, the IGF2BP3 has been gradually postulated as a valuable and potential target for cancer vaccine." (PMID 35593226, 2022). "Thus, we provided compelling evidence demonstrating that the m6A reader IGF2BP3 contributes to tumorigenesis and poor prognosis in AML and can serve as a target for the development of cancer therapeutics." (PMID 35217832, 2022). "For example, the downstream effectors and regulatory mechanisms by which IGF2BP3 exerts its roles in cancer tumorigenesis and progression have not been well documented." (PMID 34621671, 2021). "In addition, we also found that IGF2BP3 and YTHDF2 were regulated by eight different DMPs across six cancers." (PMID 33718187, 2021). "On the other hand, several cancer genes, notably IGF2BP3, IGF2, and LIPG, do not produce chimeras but are consistently upregulated by geneUIB fusions." (PMID 32631391, 2020). "Although IGF2BP3 is an oncofetal protein, which is frequently up-regulated in a variety of cancers, the DNA copy number change of it is not yet reported." (PMID 29212181, 2017). "IGF2BP3 binds to BCRP mRNA and regulates BCRP expression; this finding provides insight into the mechanism by which IGF2BP3 contributes to the aggressiveness of cancers." (PMID 26327240, 2015). "However, it should be noted that the de novo synthesis of IGF2BP3 and to a lesser extent IGF2BP1 have been reported to correlate with enhanced metastasis and poor prognosis in various cancers." (PMID 23069990, 2013). "Insulin-like growth factor 2 mRNA-binding protein 3 (IGF2BP3), an RBP known for its role in RNA metabolism, which was first demonstrated in neuronal development of mouse embryos, has been extensively studied in cancer, where it promotes proliferation, adhesion, and invasion." (PMID 40563987, 2025). "Decreased glycolytic flux may play a role, including downregulation of PKM2, an isoform of PKM specifically overexpressed in cancers, in the absence of IGF2BP3." (PMID 41015030, 2025). "However, in cancer tissues, IGF2BP1 and IGF2BP3 both tested positive." (PMID 37234166, 2023). "IGF2BP3 sustains the cellular levels of acetyl-CoA by directly binding to lncRNA TINCR and preventing its degradation, which blocks the ubiquitin-mediated degradation of ATP citrate lyase to promote lipid biosynthesis and induces cancer progression and chemoresistance." (PMID 37554271, 2023). "Because IGF2BP3 is almost absent in normal tissues other than in reproductive tissues, it may be an important target for cancer therapy." (PMID 37298373, 2023). "Moreover, different cancer-overexpressed non-coding RNAs also promote HK2 mRNA stability, with circCDKN2B-AS1 complexing with IGF2BP3 and HK2 mRNA to sustain aerobic glycolysis, while the related IGF2BP2 protein also increases HK2 mRNA stability through forming a complex with the lncRNA CASC9." (PMID 37059726, 2023). "However, a pan-cancer analysis of IGF2BP3 is not currently available, and the exact roles of IGF2BP3 in prognosis and immunology in cancer patients remain enigmatic." (PMID 36761737, 2023).
cancer (continued). "This might be due to the fact that IGF2BP1 and IGF2BP3 are oncofetal proteins that are not expressed in most adult tissues but often reactivated in cancer, whereas IGF2BP2 expression is retained throughout adulthood." (PMID 37503349, 2023). "Interestingly, while binding to m6A RNA has been established in a range of cancer types, the contribution of IGF2BP3 to the stability of these transcripts has not been fully elucidated." (PMID 36307883, 2022). "Here, we deepened the study on nine of them (ASS1, EIF4G1, GALNT7, GLUT1, IGF2BP3 (IMP3), ITGA4, RAN, SOD1, and THBS2) to ascertain whether they are truly mesothelial cancer driver genes (CDGs) or genes overexpressed in an adaptive response to the tumoral progression (“passenger genes”)." (PMID 32659970, 2020). "As a member of the critical family of m6A readers that identify the consensus GG(m6A)C sequence, IGF2BP3 participates in thousands of mRNA posttranscriptional modification through enhancing the stability and accommodation of its target mRNA (like MYC) in cancer biology." (PMID 32710725, 2020). "Therefore, we focused our attention on two related RNA binding proteins, IGF2BP1 and IGF2BP3, which bind and control CD44 mRNA stability in several cellular system and their expression is tightly related to CD44 levels in several forms of cancer." (PMID 26429859, 2015). "Additionally, circDCP2 activates the JAK-STAT signaling pathway through IGF2BP3, one of its protein partners, to promote M2 macrophages polarization via regulating the release of cytokines, which further facilitates the development and progression of CBNP-induced malignant tumors." (PMID 40770637, 2025). "However, there are still no relevant articles on IGF2BP3 and pan-cancer." (PMID 36761737, 2023). "Thus, we speculated ZC3H13, IGF2BP3, and DDX19B might participate in the occurrence and development of HCC through regulating their correlated AS events and inducing dysregulation of above cancer-related pathways." (PMID 34312475, 2021).
infection (7 papers, 2022 to 2025). The state of being infected such as from the introduction of a foreign agent such as serum, vaccine, antigenic substance or organism. "To investigate how oHSV promotes NETosis, we found that oHSV infection increased IGF2BP3 and MIB1 expression while suppressing FTO in a time-dependent manner, along with the detection of viral proteins ICP0, ICP8, and gC." (PMID 38167409, 2024). "RRM2 and insulin-like growth factor-2 messenger ribonucleic acid (mRNA)-binding protein 3 (IGF2BP3) gene knockdown was achieved by infection with lentiviruses." (PMID 38820515, 2024). "Infection with LV-IGF2BP3 resulted in marked induction of IGF2BP3 or Flag-tag." (PMID 36520532, 2023). "The level of IGF2BP3 mRNA was 21.8-fold greater than that of control after infection with the overexpression vector (p < 0.001), but 12.4 percent of that in the control group following infection with the knockdown vector (p < 0.05)." (PMID 35465321, 2022). "Furthermore, we found that the m6A readers, YTHDF2 and IGF2BP3, interacted considerably with the three lncRNAs in all infection states and promoted lncRNA stability." (PMID 36369338, 2022).
cardiovascular diseases (4 papers, 2021 to 2024). "Seven of these DMPs (25%) could be allocated to a gene that was previously associated with cardiovascular diseases (HDAC4, IGF2BP3, CASZ1, SDK1, PCDHGA1, DIO3, PTPRN2)." (PMID 34895303, 2021).
hematological malignancies (4 papers, 2021 to 2023). "Supporting our earlier observations, the IGF2BP3 mRNA was significantly associated with the proliferative “metagene” when assessed across all hematological malignancies (Mann–Whitney U test; p-value < 0.001)." (PMID 33805930, 2021).
digestive system tumors (2 papers, 2025). "The correlation between IGF2BP3 expression and clinical features of patients with gastrointestinal tumors was then analyzed." (PMID 40765570, 2025). "However, the role of IGF2BP3 in gastrointestinal tumors and its potential as a biomarker for gastrointestinal tumors are worth more exploring and summarizing." (PMID 40765570, 2025). "Additionally, research can explore whether ISL suppresses the progression of digestive system tumors through m6A/IGF2BP3-mediated stabilization of TWIST1 mRNA, and so on." (PMID 40978472, 2025).
endocrine system tumors (2 papers, 2020 to 2021). "We observed that WTAP, METTL16 and IGF2BP3 play important roles in the development of endocrine system tumors, WTAP, METTL16 are protective genes, IGF2BP3 is danger genes." (PMID 33237039, 2020). "In general, it can be considered that WTAP, METTL16 and IGF2BP3 play important roles in the development of endocrine system tumors, WTAP, METTL16 are protective genes, IGF2BP3 is danger genes." (PMID 33237039, 2020). "In general, WTAP, METTL16 and IGF2BP3 had a significant influence in the occurrence and development of endocrine system tumors." (PMID 33237039, 2020).
head and neck tumor (2 papers, 2022 to 2023). "The genetic alteration of IGF2BP3 in head and neck tumors was mainly seen in high mRNA levels, indicating that IGF2BP3 was probably regulated at the transcriptional or post-transcriptional level." (PMID 35136045, 2022). "Upstream mechanism analyses indicated that the high expression of IGF2BP3 in head and neck tumors was mainly due to mRNA level amplification." (PMID 35136045, 2022). "This study suggested that m6A methylation regulators played an important role in head and neck tumor progression and demonstrates that IGF2BP2 and IGF2BP3 were prognostic indicators and potential biomarkers for immunotherapy in OSCC and OED." (PMID 36793593, 2023).
hematological cancers (1 paper, 2021). "To get a comprehensive picture across hematological tumors, we assessed IGF2BP3 mRNA levels in 6832 hematological cancers that included 24 different disease entities." (PMID 33805930, 2021).
IGF2BP3 also shares sentences with these, for which no sentence is quoted: kidney cancer (5 papers); adenocarcinoma (3); B-cell acute lymphoblastic leukemia (3); head and neck squamous cell carcinoma (3); rheumatoid arthritis (3); acute leukemia (2); acute pancreatitis (2); diabetes (2); endocervical adenocarcinoma (2); head and neck cancer (2); uveal melanoma (2); acromelic dysplasia (1); acute liver failure (1); acute megakaryoblastic leukemia (1); acute respiratory distress syndrome (1); adenoid cystic carcinoma (1); adult T-cell leukemia (1); asthma (1); autoimmune disease (1); benign tumors (1); Burkitt lymphoma (1); central obesity (1); cerebrovascular disease (1); chronic obstructive pulmonary disease (1); colorectal tumors (1); diabetic retinopathy (1); diffuse large B-cell lymphoma (1); dysplasia (1); End-Stage Renal Failure (1); epithelioid hemangioendothelioma (1).
A further 37 diseases each share a sentence with IGF2BP3 in 1 paper.